IL4 (interleukin 4)
Diseases named in the same sentence as IL4 in open-access papers (continued):
Sharing a sentence is not in itself a finding about the gene and the disease.
breast carcinoma (continued). "This study demonstrated IL‐1β, TNF‐α, and IL‐4 as potential pathways to CRCI in response to ongoing psychological distress, which provided evidence for the involvement of psychological distress in CRCI in breast cancer survivors." (PMID 36965094, 2023). "A study in 1992 concluded that IL-4 is a non-autocrine inhibitor of breast cancer and can inhibit tumor proliferation." (PMID 37007080, 2023). "Our study suggests that breast cancer patients with psychological distress have worse cognitive functioning based on MMSE and lower quality of life, with higher levels of IL‐1β, TNF‐α, and IL‐4." (PMID 36965094, 2023). "Enhanced secretion of IL-4 from breast cancer cells could augment the M2-like polarization of macrophages in TME, which further promoted the migration of breast cancer cells." (PMID 35996149, 2022). "Enhanced secretion of IL-4 from breast cancer cells could augment the M2-like polarization of macrophages in TME, which further promotes the migration of breast cancer cells." (PMID 35996149, 2022). "A similar result was reported in a breast cancer cell line, in which rapamycin had no impact on IL4-induced 3β-HSD activity in ZR-75-1 cells." (PMID 36362361, 2022). "The transcription factor KLF4 has been shown to be a key regulator of macrophage polarization in models of both prostate and breast cancer, and is activated through STAT6 signaling; this, in turn, is triggered through IL-4 signaling and participates in limiting the pro-inflammatory response." (PMID 35359423, 2022). "For this reason, in a female mammary tumor model, we studied whether BPA treatment could affect the intratumoral expression of IL-1β, IL-4, IL-6, IL-10, TNF-α, IFN-γ, and VEGF by confocal microscopy immunofluorescence." (PMID 35269666, 2022). "Additionally, IL‐4 blockade has been shown to effectively downregulate the MAPK pathway and reduce the growth and invasion of breast cancer cells." (PMID 33682324, 2021). "Using a coculture system containing breast cancer cells and IL‐4‐activated Mφs and without direct cell‐cell contact, the shuttling of exogenous MicroRNAs from IL‐4‐activated Mφs to cocultivated breast cancer cells was observed." (PMID 33898169, 2021). "During a period of tumor metastasis, IL-4 could induce the production of MMP-9, an osteolytic cytokine, and the M2 polarization within tumorigenic microenvironment to promote metastasis of breast cancer." (PMID 34863091, 2021). "In an MMTV-PyMT breast cancer model, TAM were polarized into M2 phenotype by Th2 cell-derived IL-4." (PMID 32726950, 2020). "Our study additionally revealed a significant increase in IL-4, IL-12p40, and IL-17 expression in metastatic canine mammary tumors compared to non-metastatic tumors and healthy tissue." (PMID 32225066, 2020). "Cytokine release assays were performed to quantify relative amounts of Tc1 (IFN-γ and IL-2) and Tc2 (IL-4) cytokines secreted in co-cultured systems containing T cells (transduced or non-transduced) and breast cancer cells (TNBC and non-TNBC)." (PMID 31804974, 2019). "Similarly, high levels of IL4 and IL13 are detected in the tumor micro-environment, peripheral blood of prostate, bladder, and breast cancer patients." (PMID 31540495, 2019). "In contrast, a significantly positive correlation between expression of Sdc-1 and IL-4 (r = 0.554, P = 0.032), IL-17 (r = 0.7, P = 0.004), and Foxp3 (r = 0.539, P = 0.038) was evident in breast carcinoma tissues of non-IBC." (PMID 31145753, 2019). "Anti-inflammatory cytokines such as IL-4, IL-13, and TGF-β may polarize macrophages into M2 phenotypes which are considered immunosuppressive and can contribute to breast cancer progression by promoting growth, metastasis, and angiogenesis." (PMID 29849939, 2018). "A similar link between IL4-induced apoptosis and Stat6 has previously been reported in breast cancer, but not in AML." (PMID 28819278, 2018).
breast carcinoma (continued). "Different Th2 cytokines level assessment in the serum of patients with breast cancer, revealed a remarkably increased IL-4 in hormone-receptor negative tumors, and was related with patients’ death from cancer." (PMID 28927416, 2017). "In pulmonary metastatic model of breast cancer, Th2 CD4+ T lymphocytes that produce IL-4 and IL-13, M2-type TAMs and IMCs are activated and in turn produce EGF, thus resulting in activation of a paracrine-mediated enhancement of malignant cell invasion and dissemination." (PMID 27533463, 2016). "Similarly, the number of migrated HUVECs increased by 10-fold (p < 0.001), 12-fold (p < 0.001), and 15-fold (p < 0.001), respectively, when cocultured with MDMs activated by IL-4, MDA-MB-231, or primary breast cancer cells." (PMID 26416449, 2015). "Using qRT-PCR, we confirmed that miR-223 was overexpressed in IL-4-activated MDMs but was not highly expressed in either SKBR3 or MDA-MB-231 breast cancer cells." (PMID 21939504, 2011). "In the present study, we demonstrate that exogenous miRNAs transfected into IL-4-activated M2 macrophages can be shuttled into co-cultivated breast cancer cells in the absence of direct cell-cell contact with the macrophages." (PMID 21939504, 2011). "The shuttling of fluorescently-labeled exogenous miRNAs from IL-4-activated macrophages to co-cultivated breast cancer cells without direct cell-cell contact was observed." (PMID 21939504, 2011). "Moreover, patients with metastatic HER2 + breast cancer and a good prognosis exhibited a higher proportion of CD4 + IL-2 + T cells relative to CD4 + IL-4 + T cells, along with an increased percentage of CD56bright NK cells, in their peripheral blood compared to patients with a poor prognosis." (PMID 41582199, 2026). "The present results suggest that breast cancer survivors with PD have worse cognitive functioning based on a cognitive screening test and lower quality of life than the PD group, and significantly higher levels of IL‐1β, TNF‐α, and IL‐4, compared to the patients with NPD." (PMID 36965094, 2023). "In addition, piRNAs can also regulate gene expression at the post-transcriptional level, as in the case of piRNA-30840 which binds to IL-4 pre-mRNA, leading to its degradation, and piR-FTH1, a piRNA found in breast cancer cells, which downregulates ferritin heavy chain mRNA." (PMID 36158569, 2022). "Interestingly, MORC4 expression was selectively induced by IL‐4, whereas it was not affected by IFNγ, LPS, or a co‐culture with different breast cancer cell lines." (PMID 33377644, 2020). "Interestingly, our qPCR data demonstrate a significantly negative correlation between expression of Sdc-1 and IL-4 (r = - 0.564, P = 0.028), IL-17 (r = - 0.571, P = 0.026), and Foxp3 (r = - 0.607, P = 0.016) in breast carcinoma tissues of IBC patients." (PMID 31145753, 2019). "Primary breast cancer cells acquired sensitivity to apoptosis in vitro only in the absence of IL-4." (PMID 28609459, 2017). "In contrast, IL-4-treated macrophages (M2-type) promoted the growth of tumor cells, and lower dose (1 μM) of CHA could significantly inhibit the M2 macrophages-induced proliferation of glioma and breast cancer cells." (PMID 28045028, 2017). "Higher ELF5 expression in luminal A, but not B breast cancers, was broadly associated with the same five functional networks identified in the PyMT/Elf5 model: HGF and IL4, invasive phenotype, monocytes, immune system involvement, inflammation and the interferon response." (PMID 26717410, 2015).
breast carcinoma (continued). "For example, breast cancer patients with elevated levels of COX2 and PGE2 within the tumor and the circulation presented T cells with decreased proliferation in response to CD3 antibody stimulation, reduced levels of TNF-α, interleukin (IL)-12, IL-2, and increased levels of IL-10 and IL-4." (PMID 23029485, 2012). "Additionally, as the mouse IL‐4R/IL‐4 interaction is species‐specific in that mouse IL‐4 does cross‐react with human IL‐4R, we were unable to perform cytotoxicity assays with DABIL‐4, either against human breast cancer cell lines in vitro or with in vivo murine models of human breast cancer." (PMID 33682324, 2021). "Indeed, the breast cancer TME is infiltrated by regulatory T cells, myeloid-derived suppressor cells (MDSCs), and rich in inhibitory/Th2-polarized cytokines such as IL4, that promote tumor survival, migration and invasion, and directly inhibit Th1-polarized effector T cells." (PMID 29747685, 2018). "In solid cancers, IL4 has been shown to be useful in colorectal cancer stem cell suppression, BMP4 was found to induce glioblastoma CSCs to differentiate into non-CSCs, and salinomycin, a selective potassium ionophore, could target breast cancer stem cell proliferation and induce differentiation." (PMID 21347385, 2011). "In breast cancer, STAT6 plays a key role in inhibiting growth and inducing apoptosis, as it is activated by IL-4 independent of IRS-1." (PMID 40733498, 2025). "As IL-4 promotes oxidative phosphorylation in macrophages, TAM metabolism in breast cancer may proceed through oxidative phosphorylation rather than glycolysis." (PMID 32726950, 2020). "Generating DCs from CD14+monocytes using GM-CSF, IL-4 and maturing them with TNF-α ± IFN-α (DCT and DCTI) is a novel strategy which was based on our previous work using monocytes from patients with operable breast cancer." (PMID 19298672, 2009).
Obesity (166 papers, 2010 to 2026). Accumulation of substantial excess body fat. "IR can instigate an upsurge of inflammatory cytokines associated with obesity, including IL-1β, IL-2, IL-4, IL-5, IL-6, IL-8, tumor necrosis factor-α, and interferon, which have been robustly linked to the development of PAH." (PMID 38702735, 2024). "The results concerning the IL-4 rs1800795 polymorphism indicate a potential, albeit modest, association with obesity phenotypes." (PMID 39769263, 2024). "Future research should focus on more extensive and diverse cohort studies to validate the IL-4 polymorphism’s association with obesity across different populations." (PMID 39769263, 2024). "Recently, it was shown that the obesity-associated decreased expression of insulin receptor substrate-2 (Irs2) in macrophages attenuated the M2 macrophage activation by IL-4." (PMID 37571282, 2023). "For example, the alternative activation of AT macrophages in obesity has been reported to be inextricably linked with eosinophils by an IL-4- or IL-13-dependent process." (PMID 37720534, 2023). "Myeloid Irs2 deficiency results in enhanced FoxO1 activity in macrophages, which impairs IL-4–induced M2 macrophage activation and predisposes to developing dietary obesity and hyperinsulinemia in mice." (PMID 35700043, 2022). "The evidence suggests that CB2R activation is a therapeutic target for mitigating obesity-associated inflammation and excess lipid storage in white adipose tissue by modulating perilipin expression, upregulating IL-4, and stimulating UCP-1 signaling." (PMID 34393784, 2021). "Whereas, adipose eosinophils and IL-4 expression were reduced in mice fed HFD or in mice with genetic obesity secondary to leptin deficiency, and there was an inverse relationship between adipose eosinophil numbers and mouse weight." (PMID 32585823, 2020). "We studied the effects of IL-4 on metabolic abnormalities in a mice model of obesity involving leptin deficiency and leptin resistance." (PMID 32585823, 2020). "In summary, Fas mutation conveys resistance to high-fat diet-induced obesity by increasing IL-4 and IL-10 and by promoting thermogenic protein activity and browning." (PMID 32686763, 2020). "To extend the knowledge of biological implications of IL-4 on obesity and its complications, we studied the metabolic effects of IL-4 in two mice models of obesity: Leptin deficiency and HFD." (PMID 32585823, 2020). "Independent of leptin-deficient obesity and dietary obesity, a course of 8-week IL-4 supplementation improved obesity and impairment in Akt, STAT3, and STAT6 signaling." (PMID 32585823, 2020). "Through this study, we provided experimental evidence showing that IL-4 induced improvements of metabolic abnormalities in a mice model of obesity with leptin deficiency and HFD." (PMID 32585823, 2020). "Decreased M2a-subtype MΦ activation by IL-4 renders mice susceptible to diet-induced obesity and glucose intolerance." (PMID 30451856, 2018). "The objective of this study was to investigate the association of IL1RA and IL4 VNTRs with obesity and adiposity in 315 Malaysian subjects (128 M/187 F; 23 Malays/251 ethnic Chinese/41 ethnic Indians)." (PMID 28293435, 2017). "Interleukin-1 receptor antagonist (IL1RA) intron 2 86 bp repeat and interleukin-4 (IL4) intron 3 70 bp repeat are variable number tandem repeats (VNTRs) that have been associated with various diseases, but their role in obesity is elusive." (PMID 28293435, 2017). "As obesity results in chronic low-grade inflammation of the adipose tissue, the proinflammatory cytokine gene IL1RA and anti-inflammatory cytokine gene IL4 have VNTRs that are implicated in obesity." (PMID 28615046, 2017). "We have recently shown that obesity and diabetes are associated with an increase in the expression of IL-4, LIGHT, CCR-2, and MMP-9 in MNC and that, following gastric bypass surgery, there is a reduction in the expression of these genes." (PMID 25642424, 2015).
Obesity (continued). "Further study has indicated that the restoration of adipose tissue eosinophils (ATEs) by adoptive transfer of eosinophils from young mice to aged obese mice dampens age-related local and systemic low-grade inflammation, a hallmark of obesity, partially through IL-4 secretion." (PMID 40592472, 2025). "A few studies have shown that obesity exerts IL-4/IL-13-associated inflammatory responses." (PMID 39564133, 2024). "Additionally, haplotype analysis in the IL-4 gene and genotypic interactions will help clarify the impact on obesity risk." (PMID 39769263, 2024). "Moreover, our results are in concordance with earlier experiments that have shown that the levels of IL-4 increase during dietary-induced obesity and decrease with weight loss." (PMID 38674875, 2024). "Furthermore, IL-4 deficiency also mediates changes in macrophages in obesity through two other essential pathways." (PMID 34421909, 2021). "Published literature shows that lotus leaf reduces the levels of inflammatory cytokines IL-1β, TNF-α, IFN-γ, and IL-6, increases the levels of anti-inflammatory cytokines IL-4 and IL-10, and inhibits inflammation caused by high-fat diets accompanied by obesity." (PMID 34992717, 2021). "Currently, it remains unclear whether IL-4 has beneficial effects against leptin deficiency- and leptin resistance-provoked metabolic abnormality and obesity." (PMID 32585823, 2020). "Obesity is also associated with elevated levels of proinflammatory cytokines in the circulation and in tissues, and thus, we found that IL-1β, IL-4, and TNF-α levels in the serum were increased in the HFD group, and all of the three supplements sufficiently reduced these levels." (PMID 29023387, 2017). "This may be particularly important in models of obesity, as IL-4 has been linked to protection from metabolic dysregulation." (PMID 24465369, 2014). "Therefore, while the IL-4 rs1800795 variant may contribute to the risk of obesity, it represents only one facet of a multifactorial interplay affecting this condition." (PMID 39769263, 2024). "Therefore, obesity‐induced increases in eosinophil inflammation in the airways of asthmatic mice may be linked to the increased production of IL‐4, IL‐5, and eotaxin." (PMID 37773696, 2023). "Furthermore, our results also revealed several common upstream regulators associated with immune regulation and resistance to obesity (IL-4, IL-5, IL-33, CD15, HGF, ANGPT2, VEGFA, and neuropilin 1 [Nrp1]), supporting a critical role of intestinal homeostasis in systemic pathogenesis of obesity." (PMID 36880999, 2023). "Therefore, IL-4 deficiency in obesity increases the susceptibility of M2s to FA-induced cell death." (PMID 34421909, 2021). "As IL-4 and IL-13 have an anti-inflammatory effect in the fat metabolism, and treatment with dupilumab blocks IL-4 and IL-13, this might interfere with activation of brown fat and thus increase the risk for obesity in patients with AD." (PMID 32962676, 2020). "Obesity-influenced estrogen would enhance Th2 response, and increase the production of IL-4 and IL-13; estrogen also reduces response to inhaled corticosteroid." (PMID 41250031, 2025). "Th2 cytokines, such as IL-4, IL-5, and IL-13, regulate energy metabolism, insulin resistance, and obesity-related issues." (PMID 41007770, 2025). "This review aims to clarify the role of IL-4, IL-5, and IL-13 in contributing to the immunometabolic changes observed in obesity." (PMID 41007770, 2025). "The reduction in IL-4 levels after treatment mirrors the pattern seen in obesity, where individuals with obesity and IR exhibit significantly lower IL-4 levels in both adipose tissue and plasma compared to lean individuals." (PMID 41007867, 2025). "In patients with obesity complicated by T2D, their functional capacity appears impaired, with reduced secretion of IL-2 and IL-4, which are essential for the protective, anti-inflammatory function of these cells (particularly iNKT) in adipose tissue." (PMID 41425544, 2025).